RIPK1 (receptor interacting serine/threonine kinase 1)
Diseases named in the same sentence as RIPK1 in open-access papers (continued):
Sharing a sentence is not in itself a finding about the gene and the disease.
cancer (continued). "At low doses, these complexes are highly cytotoxic for cancer cells inducing a significant loss of cell viability that is partially decreased by Z-VAD (apoptosis inhibitor), but also by Nec-1 (RIPK1 inhibitor) and GSK872 (RIPK3 inhibitor), suggesting that both cell death routines are activated." (PMID 38806468, 2024). "In the absence of both cIAP1 and cIAP2, RIPK1 exhibits deficient polyubiquitination, resulting in reduced phosphorylation of IKKβ and decreased survival rate of cancer cells." (PMID 39769432, 2024). "Shikonin is the main active ingredient in the Chinese medicine "Zicao", which regulates PI3K/AKT/mTOR and MAPK signaling and exerts a strong anticancer effect on various types of cancer by inhibiting RIPK1/3, which ultimately inhibits cell proliferation and induces necroptosis." (PMID 37324188, 2023). "However, the human protein atlas indicates that RIPK1 production is elevated in the vast majority of cancer types." (PMID 36831413, 2023). "Notably, two keywords, RIPK1 and iron, were in burstness until 2022, which implies that the sustained prosperity of the study related to necroptosis and cancer over extended periods in the future." (PMID 37169000, 2023). "In addition to its role in cell death, RIPK1 abrogates tumor necrosis factor (TNF) signaling via nuclear factor kappa-B (NF-κB) in cancer cells." (PMID 37516007, 2023). "As a result, perhaps tumor cells can avoid the non-apoptotic cell death caused by RIPK1 or mitophagy and can aid in cancer cells’ survival by removing damaged mitochondria." (PMID 36831413, 2023). "In addition, inactivating the kinase activity of RIPK1 in cancer cells conferred minimal effects on preventing suppressive chemokine production and did not enhance TNF-mediated cytotoxicity." (PMID 37503572, 2023). "Nevertheless, a better understanding of the mechanism that regulates the cytotoxic activity of RIPK1 in immune cells may offer new therapeutic options for chronic inflammatory diseases and cancer." (PMID 36171264, 2022). "RIPK1 participates in various cancers and induces malignancy." (PMID 35907206, 2022). "It was known that expression of RIPK1 in the liver was upregulated in inflammation and cancer." (PMID 35290562, 2022). "Further, some studies reported that higher RIPK1/3 expression may promote anti-metastatic effects in cancer cells via regulating redox-metabolism to kill the metastatic cancer cells." (PMID 36361505, 2022). "However, according to the human protein atlas, the expression of RIPK1 is high in most types of cancer." (PMID 35326584, 2022). "Among them, the synergy with ferroptosis, further RIPK1/RIPK3/MLKL studies, its association with inflammation and oxidative stress and translational applications, and the therapeutic potential to treat cancer and neurodegenerative diseases are the trending research area." (PMID 35769473, 2022). "Such cancers could be targeted through necroptosis, because the absence of caspase-8 or its enzymatic activity prevents the cleavage of RIPK1 and stabilizes the necrosome." (PMID 33026575, 2021). "Therefore, further efforts understanding the precise role of RIPK1 activity in cancer models will be critical for the development of new therapies." (PMID 33567618, 2021). "Ovarian cancer cells with low caspase-8 expression are resistant to apoptosis, but when the IKKβ inhibitor IV, which suppresses the NFκB pathway, is combined with the SMAC mimetic Birinapat, which inhibits cIAP, cancer cells are forced toward necroptosis in a RIPK1-dependent manner." (PMID 33026575, 2021). "In general, we believe that RIPK3 may have a negative regulatory effect on tumorigenesis, different from RIPK1, and it has been reported in the reference that RIPK1 is involved in the NF-κB signaling pathway to regulate cancer development." (PMID 33440739, 2021). "RIPK1 plays a role in inflammation and necroptosis, and its role in cancer is complicated." (PMID 34681694, 2021).
cancer (continued). "RIPK1 expression is deregulated in certain types of human cancer tissues." (PMID 33567618, 2021). "This duality of RIPK1 function, life or death fates depending on RIPK1’s ubiquitination status mediated by the cIAPs, is what allows SMs to toggle so efficiently between these TNFα-mediated outcomes on cancer cells." (PMID 32393742, 2020). "Therefore, targeting RIPK1 has been suggested as an attractive therapeutic target for those cancers." (PMID 33036630, 2020). "Together, these data suggest that a combination of low RIPK1 and high PLK1 might be associated with chromosomal mis-segregation and long-term aneuploidy in human cancers." (PMID 30598363, 2019). "This could explain why targeting RIPK1 could contribute to the anti-cancer activities of these chemotherapeutics." (PMID 29434255, 2018). "Together, these results suggest that low expression of RIPK1 in PCTAIRE1 knockdown cancer cells potentially explains the sensitization to TNF family cytokines, but the mechanism is unclear and alternative explanations may exist." (PMID 25790448, 2015). "This suggests that RIPK1 may have a significant effect on cancer development." (PMID 40508046, 2025). "Thus, the RIPK1-NF-κB signalling axis promotes immunosuppression in surviving cancer cells, whereas decoupling of dual RIPK1 signalling in dying cancer cells can trigger the immune microenvironment to transit from suppression to activation, mediating increased ICD in cancer cells." (PMID 41334873, 2025). "Furthermore, as RIPK1 influences cell death, it may be a true biomarker and novel target for cancer diagnosis and treatment." (PMID 37516007, 2023). "Increased expression of RIPK1 confers a worse prognosis by regulating cell proliferation and inflammation, which suggests that RIPK1 may function as an oncogenic driver in cancers." (PMID 39872161, 2022). "It is still controversial whether RIPK1 should be used as a therapeutic target for cancer." (PMID 36249746, 2022). "Thus, manipulating RIPK1 checkpoints to boost its cytotoxicity in cancer cells might be an attractive therapeutic avenue in which immunogenic cell death is a desired outcome." (PMID 36171264, 2022). "Thus, enhanced RIPK1/3 levels generate excessive ROS production, and this higher ROS level might inhibit the metastatic ability of cancer cells." (PMID 36361505, 2022). "The implications of the current study are wide ranging and could be studied in the context of cancer by inducing necroptosis in cancer cells through preventing RIPK1 cleavage or autoimmune and inflammatory diseases, where RIPK1 cleavage could be induced to prevent necroptosis." (PMID 30867408, 2019). "Therefore, saponin compounds may exert anti-cancer activity via this newly-discovered RIPK1-mediated (necro) apoptosis pathway." (PMID 29760660, 2018). "In this regard, the relative ratio of RIPK1/procaspase-8 level was much higher in U118 cells than in HeLa and Jurkat cells, two cancer cell lines that readily undergo apoptosis following edelfosine treatment, and might predispose U118 cells to undergo necroptosis upon edelfosine treatment." (PMID 25593994, 2014). "Ultimately, we delve into strategies for targeting PANoptosis in cancer therapy, including targeting various molecules in the PANoptosis pathway, such as ZBP1, RIPK1, RIPK3, Caspases and other novel strategies like nanoinducers and viral vectors." (PMID 40364845, 2025). "We selected 786-O, HepG2, and MDA-MB-231, 3 cancer cell lines with high expression of SPOP and RIPK1, for further verification." (PMID 41122967, 2025). "Correlation analysis demonstrated that the expression of most of the PANoptosome components was positively correlated with CNV levels in many cancers (such as BRCA, HNSC, LUSC, and OV), especially for FADD, RIPK1, and CASP6." (PMID 38436818, 2025). "We further assessed the protein levels of SPOP, RIPK1, and RIPK3 in representative cell lines of 5 cancer types." (PMID 41122967, 2025).
cancer (continued). "Through its unique scaffold function, RIPK1 regulates immunosuppressive signals in multiple dimensions within the TME, thereby becoming a critical regulatory node for cancer immune escape." (PMID 41334873, 2025). "Given that cancer is often characterized by an imbalance between apoptosis and necroptosis, we investigated the role of the SPOP/RIPK1/RIPK3 axis in tumors." (PMID 41122967, 2025). "Necroptosis, a regulated form of necrotic cell death mediated by receptor-interacting protein kinases RIPK1 and RIPK3, and the pseudokinase MLKL, has emerged as a potential alternative pathway to induce cancer cell death." (PMID 41303584, 2025). "Key necroptotic regulators like RIPK1, RIPK3, and MLKL are often altered in cancer, allowing cells to evade necroptosis." (PMID 40893939, 2025). "Here, we have shown that Tob interacts with RIPK1 and NEMO and suppresses TNF-α-induced NF-κB activation by using cancer cell lines." (PMID 40169858, 2025). "Conversely, appropriate activation of RIPK1 activity serves as a favourable condition for necroptosis, potentially promoting ICD in cancer cells." (PMID 41334873, 2025). "The stabilisation of RIPK1’s scaffold function facilitates the assembly of complex I and activates NF-κB signalling in the TNF pathway in cancer cells." (PMID 41334873, 2025). "Thus, modulating RIPK1/RIPK3 signaling may be advantageous for overcoming cancer." (PMID 39540935, 2024). "RIPK3, a member of the receptor interacting protein kinase family, interacts with RIPK1 to form necroptotic complexes, activating MLKL and initiating necroptosis, thereby repressing cancer development." (PMID 38877579, 2024). "LD4172 induced potent RIPK1 degradation (concentration to induce 50% protein degradation DC50 = 4–400 nM) in a panel of human and mouse cancer cell lines." (PMID 39681571, 2024). "We used immunohistochemistry to detect the expression levels of RIPK1 and OTUD6B in the cancer tissues of 119 patients with LUAD and analyzed the correlation between them by statistical methods." (PMID 38880876, 2024). "MIB2 is a pro-survival E3 ubiquitin ligase that cooperates with the IAPs and TAK1 to limit the pro-apoptotic activities of RIPK1, thereby reducing TNF-mediated cancer cell death." (PMID 38156288, 2024). "In cancer cells, TNF-α signaling is mediated via NF-κB and diverted from its role in cell death by RIPK1." (PMID 37516007, 2023). "The results showed that MLKL had a strong positive correlation with CASP8, ZBP1, FASLG, RIPK1, and RIPK3 in all 33 cancer types, and RIPK3 was also strongly correlated with CASP8, MLKL, and ZBP1." (PMID 37000317, 2023). "For instance, the knockout of the necroptosis key molecules such as RIPK1, RIPK3, or MLKL in cancer cells markedly reduced tumorigenicity." (PMID 36505813, 2022). "Necroptosis is a programmed cell death mode mediated by three major mediators, RIPK1, RIPK3, and MLKL, and has been shown to play a role in various cancers." (PMID 35965497, 2022). "Through differential expression analysis, we found that MLKL was highly expressed in CRC tissues, while RIPK1 and RIPK3 were lowly expressed in cancer tissues." (PMID 36544770, 2022). "As an effective and selective RIPK1 inhibitor, PK68 had great potential in the treatment of inflammatory diseases and cancer metastasis." (PMID 36249746, 2022). "Previous studies have shown that RIPK3, RIPK1, and MLKL are the most important factors involved in necroptotic, playing important roles during cancer progression." (PMID 36110223, 2022). "Relative expressions of RIPK1, RIPK3, and MLKL proteins were significantly (0.001) elevated in both HepG2 and A549 cancer cells after treatment with the IC50 of the CM derivative, when compared to the untreated cells." (PMID 36432094, 2022). "While RIPK1, which acts in concert with RIPK3 to form fibrils and phosphorylate MLKL, is consistently preserved in cancers because it is also required for the operation of the TNF/TNFR1/NF-κB signaling axis." (PMID 32393742, 2020).
cancer (continued). "In particular, drugs targeting RIPK1, TRAIL and XIAP had opposite correlations in different cancer types with the same IAP." (PMID 31964418, 2020). "Last but not least, aurora kinase inhibitor CCT137690 can indirectly activate RIPK1, RIPK3, and MLKL in PDAC in vivo, which leads to the initiation of necroptosis and the inhibition of cancer growth and metastasis." (PMID 33665167, 2020). "Inhibiting RIPK1 with Nec-1 or downregulating of RIPK3 abrogated edelfosine-induced cell death and increased cancer cell viability." (PMID 31766571, 2019). "Among these proteins, we have identified many differentially abundant proteins identified as having a role in cancer (IFIT1, FASTKD2, PIP4K2B, ARID1B, SLC25A33: overexpressed in TR; CALD1, CPA3, B3GALT5, CD177, RIPK1: overexpressed in NR)." (PMID 29681787, 2018). "Taken together, these results indicate that single inhibition of either cIAPs or c-FLIP can sensitize cancer cells to TLR3-mediated, RIPK1/caspase-8-dependent apoptosis." (PMID 30158588, 2018). "We demonstrate that genetic knockout of necroptotic genes RIPK1, RIPK3, or MLKL in cancer cells significantly attenuated their abilities to grow in an anchorage-independent manner." (PMID 26959742, 2016). "Immunohistochemical analysis confirmed that RIPK1 and RIPK3 were expressed in colonic enterocytes and lamina propria mononuclear cells in normal tissue, and that their expression was reduced in cancer tissues." (PMID 25675296, 2015). "Inhibition of HSP90 activity in cancer cells results in degradation of client proteins, such as TYK2 and RIPK1, and reduction in NF-κB signaling, STAT3 phosphorylation and ERK activation, the changes seen in DLBCL cells treated with doxycycline." (PMID 26142707, 2015). "In the context of cancer, SPOP/RIPK1/RIPK3 axis is dysregulated across multiple cancer types, and the combination of the Smac mimetic SM164 enhances the antitumor efficacy of sunitinib in tumors with high expression of SPOP/RIPK1." (PMID 41122967, 2025). "Anti-PD1 can supply these necessary ligands by promoting TNF production, thereby sensitizing cancer cells to cell death in the absence of RIPK1." (PMID 39681571, 2024). "Additionally, investigations highlight the activation of RIPK1/RIPK3 as a critical upstream target that facilitates the initiation of tumor immunity, indicating its potential therapeutic potential in cancer treatment strategies." (PMID 39209834, 2024). "Interestingly, it has been found that necrosome-related genes (such as RIPK1, RIPK3, or MLKL) experience unspecific genetic deletions at the same rate as background genetic aberration frequency, seen in cancers." (PMID 37628814, 2023). "The phosphorylated RIPK1, in turn, represses the expression of SLC25A6, result in a transient increases in mitochondrial transmembrane potential (ΔΨm), which is highly related to cancer malignancy." (PMID 38149248, 2023). "In parallel to the first decoding of its PTMs, RIPK1-dependent necroptosis has become a sought-after target for positive and negative interference against cancer, neurodegeneration and inflammatory pathologies." (PMID 37495567, 2023). "The critical functions of RIPK1 in the regulation of non-apoptotic forms of programmed cell death suggest RIPK1 as alternative therapeutic in cancers with defective apoptosis machinery." (PMID 35159173, 2022). "On the one hand, the downregulation of the expression of numerous key molecules in necroptosis such as RIPK1, RIPK3, and MLKL has been found in different types of cancer cells, suggesting that cancer cells may evade necroptosis to survive." (PMID 36505813, 2022). "Meanwhile, homozygous CNV analysis showed that FADD in 22 cancer types, FASLG in 25 cancer types, RIPK1 in 22 cancer types, TLR3 in 15 cancer types, TNF in 23 cancer types, FAS in 15 cancer types, MLKL in 12 cancer types, and RIPK3 in 17 cancer types had homozygous amplifications." (PMID 35748782, 2022).
cancer (continued). "Therefore, RIPK1, like COX-1/2 and TSPO, is considered as a target enzyme for treatment against cancers and other inflammation diseases in multiple tissues." (PMID 35290562, 2022). "Survival analysis showed that CNVs of TNF in 22 cancer types, TLR3 in 10 cancer types, RIPK1 in 9 cancer types, FAS in 8 cancer types, FADD in 8 cancer types, RIPK3 in 7 cancer types, MLKL in 6 cancer types, and FASLG in 5 cancer types were significantly associated with overall prognosis." (PMID 35748782, 2022). "RIPK1 and RIPK3 are activators of necroptotic cell death, which has been shown to exert complex functions in diverse disease states, including infection, cancer, and sterile injury." (PMID 34333522, 2021). "RIPK1 is also a critical regulator of hepatocyte survival that cooperates with NF-ĸB to control TNFR1-dependent and -independent chronic liver inflammation and cancer." (PMID 33567618, 2021). "In addition to RIPK1, the necroptotic mediators RIPK3 and MLKL are also involved in cancer and have influence on prognosis." (PMID 33567618, 2021). "RIPK1 and CASPASE-8 were previously shown to have a cell death-independent function in the regulation of DNA-damage responses and compensatory proliferation as the basis of cancer development in the liver." (PMID 33798093, 2021). "On the other hand, a recent study demonstrated that the overexpression of receptor-interacting protein kinase 1 (RIPK1) and its consequent interaction with MCU is able to increase mitochondrial Ca2+ uptake, resulting in an increase in the proliferation of cancer cells." (PMID 33946271, 2021). "Here, we report for the first time that the key necroptotic proteins RIPK1, RIPK3 and MLKL, which have been reported to be lost or harbor reduced expression in other cancers, were expressed in both CCA primary tissues (TCGA database) and a panel of CCA cell lines." (PMID 31914150, 2020). "Using the Genomics of Drug Sensitivity in Cancer (GDSC) database for drug sensitivity and gene expression, we identified 8 drugs targeting the apoptosis pathway involving targets of BCL-2, BIRC5, Procaspases, RIPK1, TRAIL, and XIAP." (PMID 31964418, 2020). "We have identified many differentially abundant proteins already identified as having a role in cancer, such as the earlier discussed proteins IFIT1, FASTKD2, PIP4K2B, ARID1B and SLC25A33 (more abundant in TR) or CALD1, CPA3, B3GALT5, CD177 and RIPK1 (more abundant in NR)." (PMID 29681787, 2018). "We also showed that both monovalent and bivalent IAP antagonists including linker-extended compounds induced cIAP1 depletion and promoted RIPK1:caspase-8 complex formation, which correlated with their ability to degrade GFP-cIAP1 and induce cytotoxicity in cancer cell lines." (PMID 28149532, 2017). "Considering the advantageous effects of chemotherapy in promoting cancer cells apoptosis, PDAC-bearing mice were initially treated with gemcitabine for a similar impact on necroptosis, thereby confirming that chemotherapy increased expression of RIPK1/3 in vivo." (PMID 37628814, 2023). "Additionally, necroptosis may fuel carcinogenesis by inducing adaptable immunosuppression, as indicated by the upregulation of RIPK1, RIPK3, and MLKL in some aggressive cancers, including lung cancer and glioblastoma." (PMID 37612409, 2023). "Hence, either cancer cells are able to find a way to escape the non-apoptotic cell death triggered by RIPK1 or mitophagy can promote cancer cells survival, as through mitophagy damaged mitochondria can be eliminated." (PMID 35326584, 2022). "Unlike RIPK3 and MLKL, RIPK1 expression is positively correlated with cancer development." (PMID 39872161, 2022). "Among them, the synergy with ferroptosis, further RIPK1/RIPK3/MLKL studies, the mechanism and translational applications with inflammation and oxidative stress, and the therapeutic potential to treat cancer and neurodegenerative diseases might be the rising and promising research areas." (PMID 35769473, 2022).